TGIF1 (TGFB induced factor homeobox 1)
Description:
Binds to a retinoid X receptor (RXR) responsive element from the cellular retinol-binding protein II promoter (CRBPII-RXRE). Inhibits the 9-cis-retinoic acid-dependent RXR alpha transcription activation of the retinoic acid responsive element. Active transcriptional corepressor of SMAD2. Links the nodal signaling pathway to the bifurcation of the forebrain and the establishment of ventral midline structures. May participate in the transmission of nuclear signals during development and in the adult, as illustrated by the down-modulation of the RXR alpha activities.
Synonyms: TGIF; HPE4
Tractability: PROTAC: ubiquitination databases record sites on it; its protein half-life has been measured.
Gene: Protein-coding gene on chromosome 18 (3,411,608 to 3,459,978, forward strand). Ensembl gene ENSG00000177426.
Subcellular location: Nucleus
Subcellular location (Human Protein Atlas): Nucleoplasm
Pathways (Reactome):
Signal Transduction: Downregulation of SMAD2/3:SMAD4 transcriptional activity; SMAD2/SMAD3:SMAD4 heterotrimer regulates transcription
Gene Ontology:
Molecular function: DNA-binding transcription repressor activity, RNA polymerase II-specific; protein binding; RNA polymerase II cis-regulatory region sequence-specific DNA binding; sequence-specific double-stranded DNA binding; DNA-binding transcription factor activity; DNA-binding transcription factor activity, RNA polymerase II-specific; chromatin binding; co-SMAD binding; DNA binding
Biological process: negative regulation of transcription by RNA polymerase II; cellular response to growth factor stimulus; negative regulation of gene expression; regulation of DNA-templated transcription; response to xenobiotic stimulus
Cellular component: nucleoplasm; chromatin; nucleus
Genetic constraint (gnomAD): Loss-of-function variants: 4 observed, 19.18 expected, observed/expected ratio (o/e) 0.21, 90% interval 0.1 to 0.48. The upper end of that interval is the gene's LOEUF score, 0.48, which puts it in group 2 of 6, group 1 being the genes least tolerant of losing a copy. Missense variants: 275 observed, 351.31 expected, observed/expected ratio (o/e) 0.78, 90% interval 0.71 to 0.87. Synonymous variants: 122 observed, 134.16 expected, observed/expected ratio (o/e) 0.91, 90% interval 0.78 to 1.06.
Homologues: Orthologues: chimpanzee TGIF1 (98% identical), macaque TGIF1 (97% identical), pig TGIF1 (94% identical), dog TGIF1 (94% identical), rabbit TGIF1 (93% identical), mouse Tgif1 (90% identical), rat Tgif1 (87% identical), tropical clawed frog tgif1 (73% identical), zebrafish tgif1 (64% identical), Drosophila melanogaster achi (36% identical), Drosophila melanogaster vis (34% identical), Caenorhabditis elegans ceh-60 (22% identical), and 4 more. Paralogues in human: TGIF2 (44% identical), TGIF2LX (29% identical), MEIS2 (24% identical), MEIS3P2 (22% identical), MEIS3 (22% identical), PKNOX1 (22% identical), MEIS1 (22% identical), TGIF2LY (21% identical), PKNOX2 (20% identical), PBX1 (19% identical), PBX3 (18% identical), PBX2 (16% identical), and 1 more.
Diseases named in the same sentence as TGIF1 in open-access papers:
TGIF1 is named in the same sentence as 72 diseases in open-access papers, as found by Europe PMC text mining. Sharing a sentence is not in itself a finding about the gene and the disease. The quoted sentences say what the papers report.
holoprosencephaly (18 papers, 2008 to 2025). Holoprosencephaly (HPE) is a complex brain malformation resulting from incomplete cleavage of the prosencephalon, occurring between the 18th and 28th day of gestation, and affecting both the forebrain and face, which results in neurological manifestations and facial anomalies of variable severity. "TGIF1 is a transcriptional repressor playing crucial roles in human development and function and is associated with holoprosencephaly and various cancers." (PMID 34884456, 2021). "This variant was previously reported in a patient with severe holoprosencephaly and shown to affect TGIF1 function." (PMID 34440302, 2021). "We identified TGIF1 (HPE4), another holoprosencephaly-causative gene in humans." (PMID 29391420, 2018). "Loss of function mutations in TGIF1 are associated with holoprosencephaly (HPE) in humans." (PMID 27187787, 2016). "Gene mutations that impair TGIF1 function are associated with holoprosencephaly (HPE), a genetic disease with fetal craniofacial malformation." (PMID 34884456, 2021). "Similarly, the stop-gain variant in TGIF1 (MIM: 602630) is located in the first exon, where multiple PTVs in gnomAD38 are also located, but TGIF1 pathogenic variants causing holoprosencephaly are located in the final exons, where they affect DNA binding affinity." (PMID 30665703, 2019). "Mutations in the human TGIF1 gene cause holoprosencephaly (HPE), suggesting an important role for TGIF function in embryogenesis." (PMID 27187787, 2016). "Mutations in TGIF1 can cause holoprosencephaly (HPE), a severe disease affecting forebrain and craniofacial development, associated with mental retardation." (PMID 21958027, 2011). "TFs with motifs enriched in PV+ neuron OCRs that are more open in striatum relative to cortex and GPe included Tgif1, a key homeodomain gene involved in holoprosencephaly." (PMID 35576146, 2022). "A rare, heterozygous missense variant in the TALE homeobox protein gene, TGIF1 (c.268C>T:p.Arg90Cys) was found in a patient with combined pituitary hormone deficiency (CPHD), diabetes insipidus, and syndromic features of holoprosencephaly (HPE)." (PMID 34440302, 2021). "TGIF1 deletions and /or mutations have been seen in cases with holoprosencephaly but also non-affected individuals, suggesting incomplete penetrance and variable expressivity." (PMID 35331298, 2022). "Loss-of-function phenotypes for Tgif1 in mice are strain-dependent and range from no overt defect to holoprosencephaly, a brain malformation that has also been linked to TGIF1 mutations in humans." (PMID 33768097, 2021). "Although rare loss‐of‐function variants in TGIF1 are associated with holoprosencephaly, these same TGIF1 variants have not been observed in AML patients." (PMID 33058427, 2020). "Furthermore, individuals with holoprosencephaly and Tgif1‐null mice are not at increased risk for development of myeloid leukaemia, all of which argues against a function for this protein as a tumour suppressor." (PMID 33058427, 2020). "Holoprosencephaly occurs in 13q deletion syndrome (ZIC 2), 18p deletion syndrome (TGIF1), Smith Lemli Opitz (SLO, DHCR7), Hartsfield syndrome (FGFR1), Steinfeld (CDON or variants), Culler Jones (GLI2), hydrolethalus (HYLS1 and KIF7) and Pallister-Hall (GLI3)." (PMID 34576017, 2021). "Third, while some progress has been made in understanding holoprosencephaly (HPE)—particularly through the identification of variants in genes such as SHH, SIX3, ZIC2, and TGIF1—most of these findings originate from non-Latin American cohorts." (PMID 40700109, 2025). "Other gene mutations that relates to holoprosencephaly, including ZIC2, SIX3, TGIF1, CDON, FGFR1, CENPF and DHCR7, were not identified." (PMID 39859210, 2025).
colorectal cancer (8 papers, 2014 to 2026). A primary or metastatic malignant neoplasm that affects the colon or rectum. "In further support of this model, we found that overexpression of wild-type FBXW7 causes TGIF1 levels to reduce significantly in colorectal cancer cell lines that carry propellor tip mutations (LOVO, heterozygous R505C and SW1463, heterozygous R479Q)." (PMID 23676439, 2014). "In addition, TGIF1 is associated with increased breast, lung and colorectal cancer migration and metastasis." (PMID 34387307, 2021). "TGIF1, a transcriptional corepressor involved in breast and lung cancer, has also been suggested to promote colorectal cancer through activating Wnt/β-catenin signaling." (PMID 41516419, 2026). "Abnormally high expression of TGIF1 is found in colorectal cancer tissues and promotes the progression of CRC." (PMID 34912802, 2021). "In colorectal cancer, Tgif1 is indispensable for canonical Wnt activation and promotes the disease through Wnt activation." (PMID 30902975, 2019). "Taken together, our results suggest that TGIF1 is a novel colorectal tumor promoter and indicate that TGIF1 enhances colorectal cancer tumorigenesis through activating Wnt signaling." (PMID 29050273, 2017). "This study aimed to reveal the expression pattern of TGIF1 in colorectal cancer and examine the function of TGIF1 in the progression of CRC." (PMID 29050273, 2017). "Our study revealed that TGIF1 was highly expressed in colorectal cancer and promoted proliferation and migration of cancer cells." (PMID 29050273, 2017). "Overexpression of TGIF1 markedly promotes the proliferation of colorectal cancer cells both in vivo and in vitro." (PMID 29050273, 2017). "Here, we report that TGIF1 is significantly upregulated in colorectal cancers, and its high expression predicts poor prognosis." (PMID 29050273, 2017). "In CRC tissues, the nuclear β-catenin is greatly elevated, which is accompanied by enhanced TGIF1 expression, which in turn can maintain high Wnt signaling activity and thus promote colorectal cancer development." (PMID 29050273, 2017). "Instead, the homeodomain of TGIF1 is essential in promoting Wnt signaling in colorectal cancer cells, suggesting that TGIF1 may activate Wnt signaling through a different mechanism in different cell types." (PMID 29050273, 2017). "Moreover, TGIF1 activated Wnt signaling and was critical for the expression of the Wnt target genes in colorectal cancer cells, indicating that the tumor promoting function of TGIF1 is mediated by Wnt signaling." (PMID 29050273, 2017). "Therefore, disruption of this loop by inhibition TGIF1 could be a therapeutic strategy to treat colorectal cancer." (PMID 29050273, 2017). "However, it remains elusive whether TGIF1 has a general tumor promoting function in colorectal cancer." (PMID 29050273, 2017). "However, the role of TGIF1 in colorectal cancer remains unknown." (PMID 29050273, 2017). "Furthermore, shRNA-mediated 75% knockdown of FBXW7 mRNA in colorectal cancer lines with propellor tip mutations produced no significant increase in TGIF1 levels, suggesting that the monoallelic mutation produced a strong functional effect that could not readily be enhanced in the system used." (PMID 23676439, 2014). "However, we found that knockdown of TGIF1 has no obvious effects on β-catenin and Axin2 protein levels in the nuclei of colorectal cancer cells." (PMID 29050273, 2017).
breast carcinoma (6 papers, 2017 to 2022). "High abundance of the homeodomain protein TG-interacting factor 1 (Tgif1) has been associated with poor patient survival in various cancers, including upper urinary tract urothelial carcinoma, colorectal cancer, and breast cancer." (PMID 32272947, 2020). "In vitro, Tgif1-deficient osteoblasts reduced breast cancer cell migration in a Sema3E-dependent manner." (PMID 32272947, 2020). "To obtain further insights into the molecular mechanisms underlying the role of Tgif1 in the osteoblast-mediated breast cancer cell migration, we performed an unbiased RNA sequencing analysis in osteoblasts isolated from Tgif1+/+ and Tgif1−/− mice." (PMID 32272947, 2020). "Consistent with our findings, TGIF1 is overexpressed in TNBC as compared to other breast cancer subtypes and is associated with hyperactive Wnt signaling marked by increased β-catenin accumulation and its target expression." (PMID 29179446, 2017). "Besides stimulating breast cancer cell migration, an increased abundance of Tgif1 has been associated with mammary tumorigenesis." (PMID 32272947, 2020). "Furthermore, metastatic growth was attenuated in a Tgif1-deficient bone microenvironment, resulting in a reduced breast cancer-mediated bone destruction." (PMID 32272947, 2020). "Our in vitro findings suggest that Tgif1 is important for the increase of breast cancer cell migration upon stimulation with the medium that had been conditioned by osteoblasts, raising the question whether Tgif1 might also be implicated in the initiation of metastatic bone disease in vivo." (PMID 32272947, 2020). "In summary, this work demonstrates that Tgif1 in the bone microenvironment is implicated in the establishment and progression of breast cancer bone metastases and might therefore provide novel therapeutic opportunities to treat the initiation and progression of breast cancer metastasis to bones." (PMID 32272947, 2020). "We have previously identified an important role of TG-interacting factor-1 (Tgif1) in mediating interactions between breast cancer cells and osteoblasts in the bone marrow microenvironment." (PMID 35994202, 2022). "Tgif1 expression was strongly increased in osteoblasts upon stimulation by breast cancer cells, demonstrating the implication of Tgif1 in the osteoblast-breast cancer cell interaction." (PMID 32272947, 2020). "In breast cancer, long-term exposure to the carcinogen cadmium was shown to promote breast cancer cell migration and invasion by increasing the expression of Tgif1." (PMID 32272947, 2020). "Consistent with our findings using the MC3T3-E1 cell line, medium conditioned by Tgif1+/+ primary osteoblasts significantly increased breast cancer cell migration compared to control." (PMID 32272947, 2020). "In vivo deletion of Tgif1 in mice attenuates the progression of bone metastases and protects from breast cancer-induced bone destruction." (PMID 32272947, 2020). "In breast cancer, TGIF1 also behave like oncogene promoting migration, invasion and metastasis in MDA-MB-231 human breast cancer cells." (PMID 33070167, 2020). "In this study, we identified Tgif1 as a novel regulator of the osteoblast-breast cancer cell interaction." (PMID 32272947, 2020). "Semaphorin 3E (Sema3E), which is abundantly secreted by Tgif1−/− osteoblasts, dose-dependently reduced breast cancer cell migration while silencing of Sema3E expression in Tgif1−/− osteoblasts partially restored the impaired migration." (PMID 32272947, 2020). "To determine if the deletion of Tgif1 affects tumor cell homing to organs other than bones, we performed a qRT-PCR analysis to detect GFP-positive breast cancer cells in the lungs of Tgif1+/+ and Tgif1−/− mice." (PMID 32272947, 2020). "Together, our findings establish osteoblasts and Tgif1 as important regulators of breast cancer cells in the bone microenvironment and of the formation of breast cancer bone metastases." (PMID 32272947, 2020).
breast carcinoma (continued). "Here, we report that Tgif1 expression is strongly increased in osteoblasts upon stimulation by metastatic breast cancer cells, suggesting a potential role of Tgif1 in the osteoblast-breast cancer cell interaction." (PMID 32272947, 2020). "While breast cancer cells were found in approximately 78% of Tgif1+/+ mice, only 58% of Tgif1−/− mice had breast cancer cells in the bone marrow." (PMID 32272947, 2020). "Together, these results suggest that Tgif1 in osteoblasts supports breast cancer cell migration by suppressing Sema3E expression." (PMID 32272947, 2020). "It is therefore likely that Tgif1 in osteoblasts also regulates breast cancer cell migration to the metastatic site in vivo." (PMID 32272947, 2020). "In conclusion, our results suggest that Tgif1 in osteoblasts is an important regulator of breast cancer cell motility, and its presence in the bone microenvironment affects metastasis formation in the skeleton." (PMID 32272947, 2020). "In breast cancer, Tgif1 expression correlated with a poor prognosis and supported the Wnt1-driven cancer development." (PMID 30902975, 2019). "TGIF1 was shown to enhance the progression of oral squamous cell carcinoma by repressing TGF-β signaling, while in breast cancer and lung cancer, TGIF1 can promote tumor growth through activating Wnt/β-catenin signaling independently of TGF-β signaling." (PMID 29050273, 2017). "TGIF1 has been showed to promote development of mammary cancer and non-small cell lung cancer and molecular mechanisms are still not fully understood." (PMID 29050273, 2017). "It has been reported that TGIF1 is highly expressed in mammary cancer and non-small cell lung cancer and can enhance tumor progression." (PMID 29050273, 2017). "Interestingly, the deletion of Tgif1 in the bone microenvironment reduced the presence of single breast cancer cells and breast cancer micro-metastases in the bone." (PMID 32272947, 2020). "Consistently, trabecular bone volume was significantly higher in the femora of Tgif1−/− mice compared to Tgif1+/+ mice, suggesting that the lack of Tgif1 protects from breast cancer-induced bone loss." (PMID 32272947, 2020). "Given the crucial regulatory function of Tgif1 in both tumorigenesis and bone remodeling, we hypothesized that Tgif1 could also impact the initiation and progression of breast cancer bone metastases." (PMID 32272947, 2020). "While these studies established the role of Tgif1 in breast cancer cells, we determined whether Tgif1 in the tumor microenvironment affects the progression of bone metastases in a non-cell-autonomous manner." (PMID 32272947, 2020). "Here, we aimed to investigate whether Tgif1 in osteoblasts could participate in regulating the osteoblast-induced breast cancer cell migration." (PMID 32272947, 2020). "Importantly, conditioned medium collected from Tgif1−/− osteoblasts transfected with siRNA against Sema3E partially but significantly restored breast cancer cell migration to the level of medium conditioned by Tgif1+/+ osteoblasts." (PMID 32272947, 2020). "Furthermore, our results reveal that medium conditioned by osteoblasts stimulates breast cancer cell migration in a Tgif1-dependent manner." (PMID 32272947, 2020). "Together, these findings demonstrate that Tgif1 plays an important positive role during the early stages of breast cancer bone metastasis, which might be regulated by osteoblasts and vascular endothelial cells." (PMID 32272947, 2020). "A previous study has suggested that TGIF1 could sequestrate Axin1/2 in the nucleus to prevent the assembly of the destruction complex, thereby promoting Wnt signaling in breast cancer cells." (PMID 29050273, 2017). "In support of our hypothesis, immunofluorescence staining and confocal microscopy revealed that 5 days after breast cancer cell injection, the presence of tumor cells in the bone marrow microenvironment was reduced by 25% in Tgif1−/− mice compared to Tgif1+/+ mice." (PMID 32272947, 2020).